CCDC14 (coiled-coil domain containing 14)
Description:
Negatively regulates centriole duplication. Negatively regulates CEP63 and CDK2 centrosomal localization.
Synonyms: FLJ12892; DKFZp434L1050
Tractability: PROTAC: ubiquitination databases record sites on it.
Gene: Protein-coding gene on chromosome 3 (123,897,305 to 123,961,435, reverse strand). Ensembl gene ENSG00000175455.
Subcellular location: Cytoplasm, cytoskeleton, microtubule organizing center, centrosome, centriolar satellite
Subcellular location (Human Protein Atlas): Centriolar satellite; Basal body; Microtubules; Primary cilium
Gene Ontology:
Molecular function: protein binding
Biological process: protein localization to centrosome; substantia nigra development
Cellular component: centriolar satellite; centrosome
Genetic constraint (gnomAD): Loss-of-function variants: 45 observed, 53.43 expected, observed/expected ratio (o/e) 0.84, 90% interval 0.66 to 1.08. The upper end of that interval is the gene's LOEUF score, 1.08, which puts it in group 4 of 6, group 1 being the genes least tolerant of losing a copy. Missense variants: 829 observed, 872.93 expected, observed/expected ratio (o/e) 0.95, 90% interval 0.9 to 1.01. Synonymous variants: 282 observed, 308.79 expected, observed/expected ratio (o/e) 0.91, 90% interval 0.83 to 1.01.
Homologues: Orthologues: macaque CCDC14 (91% identical), chimpanzee CCDC14 (90% identical), rabbit CCDC14 (77% identical), pig CCDC14 (77% identical), dog CCDC14 (77% identical), guinea pig CCDC14 (71% identical), mouse Ccdc14 (66% identical), rat Ccdc14 (62% identical), tropical clawed frog ccdc14 (34% identical), zebrafish ccdc14 (26% identical).
Diseases named in the same sentence as CCDC14 in open-access papers:
CCDC14 is named in the same sentence as 9 diseases in open-access papers, as found by Europe PMC text mining. Sharing a sentence is not in itself a finding about the gene and the disease. The quoted sentences say what the papers report.
autism spectrum disorder (1 paper, 2020). A spectrum of developmental disorders that includes autism, and Asperger syndrome. "Huang et al36 identified CCDC14 as a candidate gene associated with autism spectrum disorder." (PMID 32485038, 2020).
infectious disease (1 paper, 2023). A disorder directly resulting from the presence and activity of a microbial, viral, or parasitic agent in humans. "TSPY4, OPN1LW, CARF, CCDC14, HNRNPCL4, SSX2B genes need further exploration as it has not been identified in any infectious disease, including the recent COVID-19 pandemic." (PMID 37644081, 2023).
CCDC14 also shares sentences with these, for which no sentence is quoted: metabolic disease (2 papers); cancer (1); epilepsy (1); Fanconi anemia (1); neurological diseases (1); Obesity (1); theileriasis (1).